ABCC2 (ATP binding cassette subfamily C member 2)
Diseases named in the same sentence as ABCC2 in open-access papers (continued):
Sharing a sentence is not in itself a finding about the gene and the disease.
bladder cancer (4 papers, 2021 to 2024). "ABCC2 is a major ATP-binding cassette transporter responsible for increasing the efflux of cisplatin and has been associated with cisplatin resistance in various cancers, including bladder cancer." (PMID 38191448, 2024). "After compiling the data, we would like to first point out that suppressing the expression of the efflux transporters ABCB1, ABCC2, SLC25A21, and ATP7A has been linked to cisplatin’s accumulation and reduced resistance in urinary bladder cancer patients." (PMID 36650399, 2023). "We concluded that the efflux transporters ABCB1, ABCC2, SLC25A21, ATP7A, and the uptake transporter OCT2, as well as the organic anion uptake transporters OAT1 and OAT2, are linked to cisplatin accumulation, toxicity, and resistance in urinary bladder cancer patients." (PMID 36650399, 2023). "Multidrug resistance transporters also contribute to DOX deprivation in cancers including bladder cancer, esophageal squamous cell carcinoma, or breast cancer, by overexpression of MRP2 (cMOAT or ABCC2) and are mainly responsible for its efflux." (PMID 38347575, 2024). "Another study found that curcumin and resveratrol resensitized a human bladder cancer cell line, T24, as well as GCB-resistant cells (T24GCB) to GCB by increasing ABCC2 expression." (PMID 36650399, 2023).
gastric cancer (4 papers, 2016 to 2025). A primary or metastatic malignant neoplasm involving the stomach. "Specifically, the ABCC2‐24C > T polymorphism was strongly associated with a favourable prognosis for gastric cancer." (PMID 39095325, 2024). "To investigate the possible role of ABCC2 in gastric cancer, we utilized our data and TCGA RNA‐seq expression profiles of gastric cancer to uncover the potential mechanisms of ABCC2 in GC." (PMID 39095325, 2024). "Intriguingly, the Kaplan–Meier survival analysis showed that patients with gastric cancer who had increased ABCC2 expression had a significantly better overall survival rate (p = 0.0015 in 1044 total cases)." (PMID 39095325, 2024). "Correlation between ABCC2 expression levels and clinicopathological features in patients with gastric cancer." (PMID 39095325, 2024). "The expression levels of ABCC2 were analyzed in 1044 gastric cancer samples from cohort 2, including 238 cases that received neoadjuvant therapy, using immunohistochemistry." (PMID 39095325, 2024). "This indicates the important role of ABCC2 in controlling amino acid metabolism and oxidative stress in gastric cancer cells." (PMID 39095325, 2024). "The spectrum of altered genes suggests that metabolic stresses may influence the biological effects of ABCC2 on gastric cancer cells." (PMID 39095325, 2024). "Our results suggest that gastric cancer cells with high ABCC2 expression can affect the regulatory function of the cellular thiol pool and redox status by promoting GSH efflux in a starved environment, leading to increased cellular susceptibility to ferroptosis, a non‐apoptotic form of cell death." (PMID 39095325, 2024). "Although it is traditionally believed that ATP binding cassette subfamily C member 2 (ABCC2) is a multidrug resistance‐associated protein correlated with a worse prognosis, our previous and several other studies demonstrated the contrary to be true in gastric cancer (GC)." (PMID 39095325, 2024). "It was found that ABCC2 is upregulated in GC and enhances glutathione (GSH) efflux, inducing metabolic vulnerability and ferroptosis in gastric cancer cells, thereby suppressing tumor growth and improving chemosensitivity." (PMID 40429829, 2025). "To further validate the role of ABCC2 in human gastric cancer, we established patient‐derived organoid (PDO) models using gastric cancer tumour tissues." (PMID 39095325, 2024). "Meanwhile, we conducted western blotting to investigate the correlation between ABCC2 expression and SLC7A11 and GPX4 in gastric cancer cell lines under different nutritional conditions." (PMID 39095325, 2024). "Interestingly, another study reported a distinct role of ABCC2 in gastric cancer (GC)." (PMID 40429829, 2025). "Moreover, GSH levels significantly decreased in the control group with high ABCC2 expression, while MDA levels correspondingly increased significantly, supporting the crucial role of ABCC2 in ferroptosis of gastric cancer cells." (PMID 39095325, 2024). "While ABCC2 is essential for the efflux of GSH from hepatocytes into the bile canaliculus, its role in glutathione metabolism and ferroptosis in gastric cancer remains unclear." (PMID 39095325, 2024).
Jaundice (4 papers, 2011 to 2024). Yellow pigmentation of the skin due to bilirubin, which in turn is the result of increased bilirubin concentration in the bloodstream. "Fourteen days after the injection with AAV8 sgRNA targeting Abcc2, L-Cas9Tg/Tg mice exhibited jaundice and phenocopied patients with ABCC2 deficiency." (PMID 38517206, 2024).
liver disease (4 papers, 2021 to 2023). "In other species such as mice, rats, or humans, mutations in ABCC2 are related to hereditary liver diseases." (PMID 37255458, 2023). "Homozygous mutations of the gene encoding Mrp2 (ABCC2) cause Dubin-Johnson syndrome, a rare liver disorder that presents with conjugated hyperbilirubinemia." (PMID 35388287, 2022).
adenoma (3 papers, 2015 to 2020). A neoplasm arising from the epithelium. "For adenoma cases, ABCC2 mRNA levels were statistically significantly increased (p = 0.037) in mild and moderate dysplasia as compared to unaffected tissue from the same individual." (PMID 25793771, 2015). "In the present study, high levels of ABCC2 gene expression were observed in adenomas with mild/moderate dysplasia similarly suggesting that ABCC2 is involved in the early development of colorectal carcinogenesis." (PMID 25793771, 2015). "In the present study we found significantly higher mRNA level of ABCC2 in adenomas with mild to moderate dysplasia and carcinoma tissue compared to the level in unaffected tissue from the same individuals." (PMID 25793771, 2015). "Interestingly, adenoma cells present a higher level of ABCC2 gene expression than carcinoma tissues." (PMID 32564237, 2020). "Our study is also in agreement with a study of ABCG2 and ABCC2 protein and ABCG2 mRNA levels in 29 adenomas from 21 patients." (PMID 25793771, 2015). "In the present study our aim was to assess the roles of ABCC2 and ABCG2 in the normal-adenoma-carcinoma sequence and we therefore measured ABCC2 and ABCG2 mRNA levels in intestinal tissues from patients with colorectal adenomas and CRC." (PMID 25793771, 2015). "In conclusion, this study found that ABCC2 and ABCG2 gene expression levels were altered in mild/moderate dysplasia in the normal-adenoma-carcinoma sequence suggesting that these ABC transporters are involved in early carcinogenesis similar to ABCB1." (PMID 25793771, 2015). "ABCC2 and ABCG2 mRNA levels were assessed in intestinal tissue from 122 CRC cases, 106 adenoma cases (12 with severe dysplasia, 94 with mild-moderate dysplasia) and from 18 controls with normal endoscopy." (PMID 25793771, 2015).
Chronic Myeloid Leukemia (3 papers, 2020 to 2022). "Finally, ABCC1/MRP1 was found as an effective transporter of imatinib from chronic myeloid leukemia (CML) cells, whereas sorafenib was proposed as a substrate for ABCC2/MRP2, therefore causing sorafenib resistance of renal carcinoma cell lines in vitro." (PMID 35327403, 2022). "In chronic myelogenous leukemia (CML), SNHG5 up-regulation stimulates imatinib resistance, through down-regulation of miR-205 and up-regulation of ABCC2 (ATP binding cassette subfamily C member 2)." (PMID 32318335, 2020).
Cirrhosis (3 papers, 2014 to 2024). A chronic disorder of the liver in which liver tissue becomes scarred and is partially replaced by regenerative nodules and fibrotic tissue resulting in loss of liver function. "Of the 26 women with a mutation in a biliary transporter (ABCB4, ABCB11, APT8B1, ABCC2), 12 (46%) had an established family history of biliary disease (ICP, cirrhosis or gallstones)." (PMID 28924228, 2017). "ABCC2 gene variants contribute to susceptibility to nonalcoholic fatty liver disease (NAFLD), which is prevalent in cases of NAFLD with cirrhosis, high BMI, and psychiatric disorders involving opioid use." (PMID 39238930, 2024).
colorectal adenocarcinoma (3 papers, 2016 to 2024). The most common type of colorectal carcinoma. "Although ABCC2 is poorly expressed in healthy colorectal epithelium, the expression of this pump is significantly elevated in colorectal adenocarcinoma." (PMID 28423714, 2017). "In addition, a recent report shows that Histone Deacetylase 1 and 2 (HDAC1 and 2) have a reciprocal relationship to RB1 and are able to reduce ABCB1 and ABCC2 gene and protein expression in colorectal adenocarcinoma and carcinoma cell lines." (PMID 26799285, 2016).
congestive heart failure (3 papers, 2018 to 2022). Failure of the heart to pump a sufficient amount of blood to meet the needs of the body tissues, resulting in tissue congestion and edema. "ABCC2 polymorphism (rs8187710, 1515G>A), among other factors, has been shown to be associated with increased odds of congestive heart failure (CHF) in patients, including children, at risk of CHF after hematopoietic stem cell transplantation with doxorubicin received pre-HCT." (PMID 36015138, 2022).
leukopenia (3 papers, 2015 to 2022). "In this study polymorphic variants in genes encoding membrane transporters, both influx (SLC22A16) and efflux ones (ABCB1, ABCG2, ABCC2), were the independent predictors of all studied symptoms of FAC myelotoxicity, excluding overall leukopenia." (PMID 29507678, 2018).
liver cancer (3 papers, 2015 to 2020). An epithelial or non-epithelial malignant neoplasm that arises from the liver. "Polymorphisms in genes modulating xenobiotics metabolism, in particular the ABCC2 c.3972C > T single nucleotide polymorphism (SNP) at exon 28, have been suggested to increase primary liver cancer (PLC) risk." (PMID 33208122, 2020). "The hepatic ABCC2 pump contributes to bile flow and is the main regulator of liver cancer chemoresistance." (PMID 26665149, 2015). "And the mechanism might be that FRD decreased the expression of ABCC2, so that the microenvironment was beneficial to the growth of liver cancer." (PMID 26665149, 2015). "The liver cancer tissues in Group D expressed high levels of both ABCC2 and OATP1B2 mRNA." (PMID 26665149, 2015). "The liver cancer tissues in Group D expressed high levels of both ABCC2 and OATP1B2 proteins." (PMID 26665149, 2015). "In conclusion, the study indicated that the Chinese Medicine JPJD could contribute to the rats with liver cancer which were pretreated with food restriction and diarrhea by regulating the expression of ABCC2 and OATP1B2 in liver tissues and cancer tissues." (PMID 26665149, 2015). "Additionally, a similar tendency of the expression of ABCC2 mRNA was observed in liver cancer tissue among these groups." (PMID 26665149, 2015). "However, little is known about the expression of OATP1B2 and ABCC2 in the liver and during liver cancer." (PMID 26665149, 2015). "The Chinese Medicine JPJD is beneficial to the liver cancer rats with decreased food intake and diarrhea by upregulating the expression of the ABCC2 and downregulating the OATP1B2 in liver tissues while downregulating ABCC2 and upregulating OATP1B2 in cancer tissues." (PMID 26665149, 2015). "However, further research is needed to determine whether JPJD positively impacts the liver microenvironment during liver cancer by regulating the levels of OATP1B2 or ABCC2." (PMID 26665149, 2015). "It was consistent with the previous studies that JJD could downregulate ABCC2 and upregulate OATP1B2 in liver cancer tissue." (PMID 33424998, 2020). "However, in the liver cancer tissues of LC rats, the expression level of the OATP1B2 protein was lower than the expression level of the ABCC2 proteins." (PMID 26665149, 2015). "Furthermore, previous studies have provided no direct evidence of the roles of OATP1B2 and ABCC2 during the pathological progression of liver cancer." (PMID 26665149, 2015).
neuropathy (3 papers, 2015 to 2023). A disorder affecting the nervous system that manifests with pain, tingling, numbness, and/or muscle weakness. "Studies of NPY-LA with more participants having long-duration T1D and T2D and including identifications of genetic variants are needed to further elaborate associations between DCAF5, ABCC2, NPY-LA, and neuropathies." (PMID 35627254, 2022). "ABCC2 and GSTP1 were associated with both platinum- and taxane-induced neuropathy; CYP2C8 was associated with both taxane- and platinum/taxane-induced neuropathy; and ERCC1 was associated with platinum- and platinum/taxane-induced neuropathy." (PMID 26269716, 2015). "Since we assume that NPY levels are diminished in the presence of NPY-LA, we hypothesize there is a possible association between NPY-LA levels, neuropathy, gene variants of DCAF5, and the function of ABCC2." (PMID 35627254, 2022). "Although significant associations were found between SNPs in ABCA1 (rs2230806), ABCC2 (rs1885301, rs3740066, rs4148396) and CAMK2N1 (rs12023000) and CIPN in univariate analyses, none of these SNPs were associated with neuropathy in multivariate setting." (PMID 36672910, 2023).
Pseudoxanthoma elasticum (3 papers, 2014 to 2024). "Moreover, genetic mutations in ABC transporters have been linked to various human diseases, like Dubin–Johnson syndrome (ABCC2), Tangier disease (ABCA1), or Pseudoxanthoma elasticum (ABCC6)." (PMID 25064003, 2014).
Thrombocytopenia (3 papers, 2014 to 2025). A reduction in the number of circulating thrombocytes. "ABCC2 rs3740066(C3972T, Ile1324Ile) T allele was suggested as a risk factor for grade 3-4 thrombocytopenia in 445 NSCLC patients receiving platinum-based chemotherapy (OR = 2.43; 95% CI: 1.06–5.56; p = 0.034)." (PMID 39234108, 2024). "Our study found patients with T allele on ABCC2 rs717620 had a higher risk of thrombocytopenia." (PMID 40832604, 2025). "Female, furosemide, rs1801133, ABCG2 rs2231142, ABCC2 rs717620 were related to more thrombocytopenia, while rs1045642 and high ALB were related to less." (PMID 40832604, 2025).
acute tubular necrosis (2 papers, 2024). "The aim of this study was to investigate the influence of single nucleotide polymorphisms in genes encoding metabolizing enzymes (CYP3A5) and transporters (ABCC2) on clinical outcomes (acute graft failure and/or acute tubular necrosis (ATN)) in kidney transplant recipients (KTR)." (PMID 38673067, 2024).
arterial hypertension (2 papers, 2017 to 2022). "We also found significant associations between variants present in ABCC2 gene (rs2273697 GA, rs717610 CT and rs3740066 TT) and clinical events, but protective ones in this case, such as a reduced risk of arterial hypertension and a significantly lower incidence of chronic nephrotoxicity." (PMID 35214086, 2022). "In arterial hypertension, we found associations of variants in ABCB1 and ABCC2 genes of the recipient with lower risk." (PMID 35214086, 2022). "Other variants in different locations of SLCO1A2, ABCC2 and ABCB1 transporter genes were associated with a lower risk of suffering from type 2 diabetes mellitus, chronic and acute nephrotoxicities and arterial hypertension." (PMID 35214086, 2022). "Polymorphisms including apolipoprotein L1 (APOL1), ATP-Binding Cassette Subfamily B Member 1 (ABCB1), Caveolin 1 (CAV1), and ATP-Binding Cassette Subfamily C Member 2 (ABCC2) have been shown to affect graft survival, hypertension, and calcineurin-induced nephrotoxicity." (PMID 28507980, 2017).
colorectal adenoma (2 papers, 2015 to 2019). An adenoma that arises from the colon or rectum. "Different studies reported that the increased ABCC2 gene expression is an early event during the transition from colorectal adenoma to carcinoma, and that the ABCC2 expression level seems to be regulated by sex hormones." (PMID 31395900, 2019).
COVID-19 (2 papers, 2021 to 2022). A disease caused by infection with severe acute respiratory syndrome coronavirus 2. "Variants in CYP3A4, CYP3A5, CYP2C8, CY2D6, ABCB1, ABCC2, and SLCO1B1, among other variants, could be included in pharmacogenetic studies of COVID-19 treatment." (PMID 33807592, 2021).
esophageal cancer (2 papers, 2013 to 2020). A primary or metastatic malignant neoplasm involving the esophagus. "Available studies suggest that expression of several ABC proteins (ABCB1, ABCC2, and ABCG2) correlates with prognosis or response to therapy in esophageal cancer patients." (PMID 33390934, 2020).
fatty liver (2 papers, 2015 to 2021). "Common SNPs in ENPP1 and ABCC2 have suggestive association with fatty liver, but with less compelling significance." (PMID 26740948, 2015). "Additionally, we analyzed the mRNA levels of pregnane X receptor (PXR) and ATP-binding cassette transporter isoform C2 (ABCC2), which play important roles in hepatic triglyceride accumulation and are critical mediators of liver steatosis and steatohepatitis development." (PMID 34206460, 2021).
gallstones (2 papers, 2017 to 2023). Solid crystalline precipitates in the biliary tract, usually formed in the gallbladder, resulting in the condition of cholelithiasis. "Additionally, the downregulated proteins in gallstone bile showed enrichment in bile acid and bile salt transport (padjusted = 0.004), which included AKR1C1, ABCC2, ABCB11, and ATP8B1." (PMID 38111640, 2023).
kidney transplant (2 papers, 2023 to 2024). A surgical procedure in which one or both kidneys from a donor are implanted into a recipient. "The use of PBA in IR injury affected the levels of the ABC transporter genes (Abcc2, Abcc5, and Abcg2), significantly suppressed inflammation and oxidative stress, reduced ER stress, and thus significantly mitigated liver IR injury." (PMID 38168520, 2023).
lung adenocarcinoma (2 papers, 2016 to 2022). A carcinoma that arises from the lung and is characterized by the presence of malignant glandular epithelial cells. "Differentially expressed ABCC2 and ABCC5 are considered as diagnostic biomarkers of lung adenocarcinoma, while ABCC2, ABCC6, and ABCC8 are reportedly associated with its prognosis." (PMID 35837087, 2022).
malignant neoplasm of the prostate (2 papers, 2022 to 2025). "In contrast, prostate cancer tissues exhibited frequent deep deletions in ABCG2, ABCG1, ABCC4, ABCA2, ABCC2, ABCC7/CFTR, and ABCC9." (PMID 40641097, 2025).
metastatic colorectal cancer (2 papers, 2020 to 2025). "A total of 132 metastatic colorectal cancer patients were genotyped for CYP3A4*1B, CYP3A4*18, CYP3A5*3, DPYD*2A, DPYD*5, DPYD c.1774C > T, UGT1A1*28, UGT1A1*6, ABCB1 c.1236C > T, ABCB1 c.3435C > T, ABCC2 c.3972C > T, and ABCG2 c.421C > A." (PMID 32778670, 2020). "A clinical study in metastatic colorectal cancer (CRC) patients demonstrated significantly higher tumour MRP2 expression in non-responders to oxaliplatin-based combination chemotherapy, correlating to elevated ABCC2 mRNA with reduced intracellular drug accumulation and oxaliplatin resistance." (PMID 40867257, 2025).
papillary renal cell carcinoma (2 papers, 2025 to 2026). A rare subtype of renal cell carcinoma, arising from the renal tubular epithelium and showing a papillary growth pattern, which typically manifests with hematuria, flank pain, palpable abdominal mass or nonspecific symptoms, such as fatigue, weight loss or fever. "In IHC analysis, this subtype, which the authors named “oncocytic low grade papillary renal cell carcinoma”, was positive for GATA3, negative for CA IX, and strongly and diffusely positive for ABCC2 (similarly to PRCC type II)." (PMID 40989704, 2025).